DCAF7 (DDB1 and CUL4 associated factor 7)
Description:
Involved in craniofacial development. Acts upstream of the EDN1 pathway and is required for formation of the upper jaw equivalent, the palatoquadrate. The activity required for EDN1 pathway function differs between the first and second arches (By similarity). Associates with DIAPH1 and controls GLI1 transcriptional activity. Could be involved in normal and disease skin development. May function as a substrate receptor for CUL4-DDB1 E3 ubiquitin-protein ligase complex.
Synonyms: HAN11; WDR68; SWAN-1; AN11
Tractability: PROTAC: ubiquitination databases record sites on it; its protein half-life has been measured.
Gene: Protein-coding gene on chromosome 17 (63,550,222 to 63,594,286, forward strand). Ensembl gene ENSG00000136485.
Subcellular location: Cytoplasm; Nucleus
Subcellular location (Human Protein Atlas): Nucleoplasm; Cytosol
Pathways (Reactome):
Metabolism of proteins: Association of TriC/CCT with target proteins during biosynthesis; Neddylation
Gene Ontology:
Molecular function: protein binding; protein-macromolecule adaptor activity
Biological process: protein ubiquitination
Cellular component: Cul4-RING E3 ubiquitin ligase complex; cytosol; nuclear matrix; nucleoplasm; protein-containing complex; Cul4A-RING E3 ubiquitin ligase complex; Cul4B-RING E3 ubiquitin ligase complex; cytoplasm; nucleus
Genetic constraint (gnomAD): Loss-of-function variants: 4 observed, 38.92 expected, observed/expected ratio (o/e) 0.1, 90% interval 0.05 to 0.23. The upper end of that interval is the gene's LOEUF score, 0.23, which puts it in group 1 of 6, group 1 being the genes least tolerant of losing a copy. Missense variants: 128 observed, 456.39 expected, observed/expected ratio (o/e) 0.28, 90% interval 0.24 to 0.32. Synonymous variants: 143 observed, 172.07 expected, observed/expected ratio (o/e) 0.83, 90% interval 0.73 to 0.95.
Homologues: Orthologues: chimpanzee DCAF7 (100% identical), guinea pig DCAF7 (100% identical), mouse Dcaf7 (100% identical), pig DCAF7 (100% identical), rabbit DCAF7 (100% identical), rat Dcaf7 (100% identical), tropical clawed frog dcaf7 (99% identical), dog DCAF7 (99% identical), zebrafish dcaf7 (98% identical), Drosophila melanogaster wap (86% identical), Caenorhabditis elegans swan-2 (64% identical), Caenorhabditis elegans swan-1 (52% identical).
Diseases named in the same sentence as DCAF7 in open-access papers:
DCAF7 is named in the same sentence as 40 diseases in open-access papers, as found by Europe PMC text mining. Sharing a sentence is not in itself a finding about the gene and the disease. The quoted sentences say what the papers report.
hepatocellular carcinoma (2 papers, 2025 to 2026). A malignant tumor that arises from hepatocytes. "In conclusion, this study positions DCAF7 as a multi‐layered oncogenic driver that integrates genetic, epigenetic and immune cues across cancers, with particularly strong evidence of Wnt‐mediated tumour‐promoting activity in hepatocellular carcinoma." (PMID 41472554, 2026). "Validation experiments were confined to hepatocellular carcinoma; whether the same molecular circuits operate in other DCAF7‐high tumours remains to be tested in lineage‐appropriate cell lines, organoids and animal models." (PMID 41472554, 2026). "However, the precise function of DCAF7 in regulating the progression of hepatocellular carcinoma (HCC) ferroptosis remains elusive." (PMID 40877242, 2025).
liver cancer (2 papers, 2022 to 2025). An epithelial or non-epithelial malignant neoplasm that arises from the liver. "First, we revealed that DCAF7 mRNA was significantly highly expressed in liver cancer tissues compared to paired adjacent normal tissues, particularly in HCC through the UALCAN database." (PMID 40877242, 2025). "In addition, TSC1 overexpression resulted in poor outcomes in liver cancer patients (p < 0.05), but DCAF7 and EPS15 might not be associated with poor outcomes in liver cancer patients (both p > 0.05)." (PMID 35655269, 2022).
lung adenocarcinoma (2 papers, 2026). A carcinoma that arises from the lung and is characterized by the presence of malignant glandular epithelial cells. "Analysis of The Cancer Genome Atlas (TCGA) data revealed that seven DCAF genes (DCAF2, DCAF4, DCAF7, DCAF12, DCAF13, DCAF15, and DCAF17) were significantly upregulated in lung adenocarcinoma (LUAD)." (PMID 41047465, 2026).
nasopharyngeal carcinoma (2 papers, 2024 to 2025). A carcinoma arising from the nasopharyngeal epithelium. "Emerging evidence has implicated DCAF7 as an oncogenic driver in various malignancies, including pancreatic neuroendocrine tumors and nasopharyngeal carcinoma." (PMID 40877242, 2025). "As DCAF7 has been implicated in regulating drug sensitivity in pancreatic neuroendocrine tumors and nasopharyngeal carcinoma, we sought to investigate its potential involvement in modulating sorafenib response in HCC." (PMID 40877242, 2025). "Recently, DCAF7 was identified as a critical modulator of drug sensitivity and plays important roles in pancreatic neuroendocrine tumors and the metastasis of nasopharyngeal carcinoma." (PMID 40877242, 2025).
prostate carcinoma (2 papers, 2008 to 2022). A carcinoma that arises from epithelial cells of the prostate gland. "In comparison, there were no obvious associations between the expression levels of ABHD2, FGF2, DCAF7, GSK3B, NACC2, DICER1, and FGFR1OP genes and survival rate in prostate cancer patients." (PMID 36468011, 2022).
viral infection (2 papers, 2025). "We observed that PAK2 activation is a critical priming step for TFEB degradation as this kinase is activated by viral infection, generating a phospho-degron required for subsequent DCAF7 recognition (see the model in fig." (PMID 40465712, 2025). "To further validate the impacts of DCAF7 on TFEB protein and viral infection, we reexpressed DCAF7 in DCAF7 KO cells." (PMID 40465712, 2025). "As our DCAF7 inhibitors demonstrated the capacity to modulate basal TFEB levels and lysosomal activity, we next sought to explore the utility of these compounds in the setting of viral infection, where the DCAF7-dependent degradation of TFEB is markedly augmented." (PMID 40465712, 2025). "The function of DCAF7 in virus infection has been poorly studied." (PMID 40145735, 2025). "In the absence of viral infection, DCAF7 KO cells demonstrated an approximately twofold increase in their TFEB protein levels compared to wild-type (WT) control cells." (PMID 40465712, 2025).
breast carcinoma (1 paper, 2026). "Within this framework, we found that DCAF7 is mutated in most malignancies, with the highest alteration rate in breast cancer." (PMID 41472554, 2026). "To assess whether the oncogenic role of DCAF7 extends beyond LIHC, we focused on breast cancer, in which DCAF7 is highly expressed and explored its biological effects in the BT549 cell line." (PMID 41472554, 2026).
cervical squamous cell carcinoma (1 paper, 2026). A squamous cell carcinoma arising from the cervical epithelium. "PFI analysis mirrored these findings – overexpression of DCAF7 portended earlier progression in ACC, cervical squamous cell carcinoma and endocervical adenocarcinoma (CESC), LIHC and uveal melanoma (UVM), while continuing to confer a protective effect in KIRC." (PMID 41472554, 2026).
cleft lip (1 paper, 2022). Congenital defect in the upper lip where the maxillary prominence fails to merge with the merged medial nasal prominences. "DCAF7 is required for zebrafish craniofacial development and a genome-wide association study of single nucleotide polymorphisms in a multi-ethnic group of patients identified DCAF7 as a risk locus for cleft lip and cleft palate." (PMID 36248734, 2022).
Crohn disease (1 paper, 2012). A gastrointestinal disorder characterized by chronic inflammation involving all layers of the intestinal wall, noncaseating granulomas affecting the intestinal wall and regional lymph nodes, and transmural fibrosis. "Additionally, DDB1- and CUL4-associated factor 7 (DCAF7), the human homolog of SWAN-1, is differentially regulated in the intestinal epithelium and in blood from patients suffering from Crohn's disease or ulcerative colitis, two forms of inflammatory bowel disease." (PMID 22792069, 2012).
glioblastoma multiforme (1 paper, 2026). "CPTAC proteomics corroborated the transcript findings that DCAF7 protein was markedly increased in BRCA, COAD, LUAD, pancreatic adenocarcinoma (PAAD) and LIHC, but decreased in UCEC, HNSC and glioblastoma multiforme (GBM)." (PMID 41472554, 2026).
glioma (1 paper, 2026). A benign or malignant brain and spinal cord tumor that arises from glial cells (astrocytes, oligodendrocytes, ependymal cells). "We observed that high DCAF7 aligned with elevated TMB in LUAD, BRCA, stomach and oesophageal carcinoma (STES), sarcoma (SARC), pan‐kidney cohort (KIPAN), STAD and HNSC and with increased MSI in glioma (GBMLGG), CESC, LUSC, LIHC and CHOL." (PMID 41472554, 2026).
Insulin resistance (1 paper, 2022). Increased resistance towards insulin, that is, diminished effectiveness of insulin in reducing blood glucose levels. "Given that we show DCAF7 regulates insulin signaling in vitro, and dFoxo localization in Drosophila tissue, a limitation of this study is that a role for DCAF7 in glucose metabolism and the development of insulin resistance was not examined." (PMID 36248734, 2022).
medulloblastoma (1 paper, 2020). A malignant, invasive embryonal neoplasm arising from the cerebellum. "The decrease in the levels of DCAF7 can lead to impairment of DNA repair, thereby increase the radiation sensitivity of medulloblastoma cells upon miR-193a expression." (PMID 32410663, 2020). "Thus, the downregulation of STMN1 and DCAF7 may contribute to the tumor-suppressive activity of miR-193a by decreasing proliferation, inducing apoptosis, and increasing radiation sensitivity of medulloblastoma cells." (PMID 32410663, 2020).
melanoma (1 paper, 2024). A malignant, usually aggressive tumor composed of atypical, neoplastic melanocytes.
neuroblastoma (1 paper, 2024). Neuroblastoma (NB) is the most common solid, extracranial childhood tumor. "The mechanism by which PHLDA1 is involved in regulation of neuroblastoma differentiation might relay on its direct interaction with DCAF7/AUTS2 complex, what might lead to alteration in the AUTS2 isoforms balance observed in this study." (PMID 38495105, 2024).
osteosarcoma (1 paper, 2011). A usually aggressive malignant bone-forming mesenchymal neoplasm, predominantly affecting adolescents and young adults. "CDK 9 overexpression also increased proliferation of human osteosarcoma cell line U20S2, while CRK, CDK9, DCAF7, NEK6, GNB1, SPOP, and WW2 also increased proliferation in mouse fibroblasts." (PMID 21629697, 2011).
psoriasis (1 paper, 2022). An autoimmune condition characterized by red, well-delineated plaques with silvery scales that are usually on the extensor surfaces and scalp. "For immune cells, T cells and Monocytes were related to PEBP1, MDM2, TIMM9 and DCAF7 in psoriasis group." (PMID 36685512, 2022).
cancer (9 papers, 2008 to 2026). A tumor composed of atypical neoplastic, often pleomorphic cells that invade other tissues. "DCAF7 is frequently activated by genetic and epigenetic mechanisms across cancers, associates with an immunotherapy‐relevant tumour immune milieu, and drives Wnt/β‐catenindependent malignant phenotypes in LIHC." (PMID 41472554, 2026). "Across cancers, DCAF7 showed positive associations with the majority of writers, erasers and readers for all three marks." (PMID 41472554, 2026). "Elucidating the precise molecular basis of these expression differences is therefore essential for understanding the functional consequences of DCAF7 dysregulation across cancer contexts." (PMID 41472554, 2026). "Our pan‐cancer analysis revealed tissue‐specific expression patterns of DCAF7, with significant down‐regulation in KICH at the RNA level compared with corresponding normal tissues, and in UCEC, HNSC and GBM at the protein level." (PMID 41472554, 2026). "Across cancers, DCAF7 copy number correlated positively with mRNA abundance, implicating gene dosage in transcriptional up‐regulation." (PMID 41472554, 2026). "DCAF7 was overexpressed in most cancers, consistent with copy‐number gain, focal promoter hypomethylation and putative m6A‐linked post‐transcriptional regulation, whereas hypermethylation at two CpG loci predicted poor prognosis in LIHC." (PMID 41472554, 2026). "It is worth mentioning that DCAF7 showed increased levels in nearly all solid tumors compared to the normal tissues, with elevated DCAF7 expression correlating with a negative prognosis, suggesting a significant involvement of DCAF7 in cancer development." (PMID 38973296, 2024). "Given the significance of ZBTB33/Kaiso function in the neurological processes and cancer, further investigation of the functional interaction between DCAF7, DYRK1A and Kaiso is justified." (PMID 37900285, 2023). "In our analysis, DCAF7 expression showed robust positive associations with the infiltration of multiple immune subsets – including B cells, endothelial cells, macrophages, NK cells and both CD4+ and CD8+ T lymphocytes – across cancers." (PMID 41472554, 2026). "DDB1 and CUL4‐associated factor 7 (DCAF7) is a WD‐repeat adaptor that recruits substrates to the CUL4DDB1 ubiquitinligase complex, but its pan‐cancer relevance and mechanistic contribution to tumor progression remain unclear." (PMID 41472554, 2026). "While CDH2 and CEACAM6 are known to have elevated expression in various cancers, to the best of our knowledge no clear role or association between DCAF7 and cancer has so far been described." (PMID 41160880, 2026). "Moreover, whereas AXIN1 is tightly controlled by tankyrase‐mediated PARsylation and ubiquitination, DCAF7 up‐regulation tracks with copy‐number gain and epigenetic/RNA‐modification changes in our pan‐cancer analysis." (PMID 41472554, 2026). "DCAF7 expression correlated positively with most of 60 evaluated ICPs across cancers." (PMID 41472554, 2026). "This convergence of genetic lesions, DNA‐ and RNA‐level epigenetic alterations strongly suggests that diverse oncogenic pressures co‐opt DCAF7 to support malignant growth and highlights its potential utility as an integrated genomic–epigenomic biomarker across cancer types." (PMID 41472554, 2026). "Collectively, these multi‐platform data indicate that DCAF7 shapes the immune milieu by influencing lymphocyte subsets, checkpoint‐gene expression and genomic‐instability metrics, thereby positioning it as a potential modulator of anti‐tumour immunity across cancers." (PMID 41472554, 2026). "Moreover, positive associations between DCAF7 and TMB, MSI or NEO in several cancers suggest that DCAF7 may also influence the antigenic landscape, further modulating anti‐tumour immunity and potential treatment response." (PMID 41472554, 2026).
cancer (continued). "Given the consistent correlation between elevated DCAF7 expression and adverse clinical outcomes in LIHC, we selected LIHC as the primary cancer type to investigate DCAF7 functional role in tumour progression." (PMID 41472554, 2026). "Our results showed that majority hub genes DCAF7, FGF2, GSK3B, NACC2, and NFIB were highly expressed and (nTPM >19) localised mainly in the nuclei of the cancer cells." (PMID 36468011, 2022). "The results showed that ABHD2, DCAF7, and GSK3B were upregulated in cancer tissues compared with normal prostate tissues with high or medium intensity." (PMID 36468011, 2022). "Taken together, these data indicate that DCAF7 promotes a proliferative, adhesion‐competent transcriptional program, particularly in LIHC, while variably modulating lineage‐specific functional states across cancers." (PMID 41472554, 2026). "Genes enriched in DCIS cells from asymmetric lineages included known markers of cancer invasiveness such as CDH245, but also genes with unknown roles in cancer progression, such as DCAF7 and LINC01999." (PMID 38553478, 2024). "While, e.g., DCAF7 and CDH2 displayed continuous changes across lineage types occurring during cancer progression, others such as TCIM or BRIP1 were expressed transiently at higher levels in asymmetric or only in symmetric (i.e., only invasive tumor cell) lineages, respectively." (PMID 38553478, 2024). "Other genes like HNRNPA0, DCAF7, and TRIM52 functioned in diverse ways including abnormal changes in alternative splicing or activation of canonical signal pathways in relation with cancer progression." (PMID 33134164, 2020). "Except for tumour types lacking GTEx controls, DCAF7 was significantly higher in most cancers." (PMID 41472554, 2026). "Despite these isolated observations, a systematic, pan‐cancer evaluation of DCAF7 has been lacking." (PMID 41472554, 2026). "Researchers had identified ZNF703 as a cofactor of a nuclear complex covering DCAF7, PHB2 and NCOR2 through mass spectrometry and pointed out that ZNF703 expression could result in the activation of stem cell-related gene expression leading to an increase in cancer stem cells." (PMID 27764785, 2016).